LINC01123 (long independently transcribed non-coding RNA 1123)
Synonyms: YG-6
Gene: Long non-coding RNA gene on chromosome 2 (109,986,977 to 110,019,161, forward strand). Ensembl gene ENSG00000204588.
Diseases named in the same sentence as LINC01123 in open-access papers:
LINC01123 is named in the same sentence as 11 diseases in open-access papers, as found by Europe PMC text mining. Sharing a sentence is not in itself a finding about the gene and the disease. The quoted sentences say what the papers report.
colon cancer (4 papers, 2020 to 2025). "At the subcellular level, LINC01123 predominantly localizes to the cytoplasm in six types of cancer cells: colon cancer, breast cancer, HNSCC, LUAD, NSCLC, glioma." (PMID 40255398, 2025). "In colon cancer, LINC01123 localizes predominantly in the cytoplasm, where it competes with VEGFA for binding to miR-34c-5p." (PMID 40255398, 2025). "LINC01123 depletion hinders colon cancer cell proliferation." (PMID 35965536, 2022). "Nevertheless, limited papers have discussed the function of LINC01123 in colon cancer." (PMID 32700743, 2020). "LINC01123 could act as an oncogene and promote colon cancer malignancy and chemoresistance." (PMID 35965536, 2022). "Therefore, we proposed a hypothesis that LINC01123 might serve as a competing endogenous RNA (ceRNA) in colon cancer." (PMID 32700743, 2020).
non-small cell lung carcinoma (3 papers, 2019 to 2025). A group of at least three distinct histological types of lung cancer, including non-small cell squamous cell carcinoma, adenocarcinoma, and large cell carcinoma. "Another example was LINC01123, which was upregulated in non-small-cell lung cancer (NSCLC) patients with high 18F-FDG uptake on PET/CT scans and correlated with poor survival." (PMID 40126351, 2025).
head and neck squamous cell carcinoma (2 papers, 2019 to 2022). A squamous cell carcinoma that arises from any of the following anatomic sites: lip and oral cavity, nasal cavity, paranasal sinuses, pharynx, larynx, and salivary glands. "LINC01123 was reported to be a novel and important prognostic factor in head and neck squamous cell carcinoma." (PMID 31186036, 2019).
lymph node metastasis (2 papers, 2025). "This revealed why LINC01123 upregulation was an indicator of lymph node metastasis and advanced TNM stage in CCA." (PMID 39840861, 2025). "In CRC, higher LINC01123 expression is observed in patients with advanced TNM stage and lymph node metastasis." (PMID 40255398, 2025).
acute myeloid leukemia (1 paper, 2019). Acute myeloid leukemia (AML) is a group of neoplasms arising from precursor cells committed to the myeloid cell-line differentiation. "Among these, some have been reported in other cancers, such as LINC01123 in prostate cancer, LINC00677 in acute myeloid leukemia and LINC00462 in pancreatic cancer." (PMID 31242667, 2019).
glioma (1 paper, 2025). A benign or malignant brain and spinal cord tumor that arises from glial cells (astrocytes, oligodendrocytes, ependymal cells). "In glioma, LINC01123 is significantly upregulated in radioresistant cells (U251R), where it acts as a ceRNA by binding to miR-151a." (PMID 40255398, 2025).
tumor (5 papers, 2019 to 2025). "Moreover, LINC01123 facilitates not only cell migration and invasion but also induces a stem-like phenotype associated with tumor-initiating properties." (PMID 40255398, 2025). "In conclusion, LINC01123 has emerged as a newly identified and dysregulated cancer-associated lncRNA, highlighting its potential as both a promising biomarker and a key player in multiple critical aspects of tumor progression, metabolism, immune evasion, and therapeutic resistance." (PMID 40255398, 2025). "The functional consequences of this interaction are substantial; experimental studies have demonstrated that through these RNA-protein complexes, LINC01123 not only influences splicing but also promotes tumor growth and migration." (PMID 40255398, 2025). "Given its pivotal role in tumor progression, LINC01123 is expected to serve as a valuable tumor biomarker and contribute to the development of effective therapeutic strategies across various malignancies." (PMID 40255398, 2025). "LINC01123 emerges as a critical regulator of tumor cell malignancy, exerting its effects through intricate ceRNA networks and signaling pathways." (PMID 40255398, 2025). "In vivo and in vitro experiments further demonstrate that LINC01123 influences diverse cellular processes, including proliferation, apoptosis, viability, migration, invasion, stemness, and tumor growth." (PMID 40255398, 2025). "LINC01123 plays a critical role in shaping the tumor microenvironment through its dual regulation of metabolism and immunity in cancer." (PMID 40255398, 2025). "The effects of LINC01123, B7–H3, and miR-214-3p on tumor progression, CD8+T-cell-mediated immune response, and the tumorigenicity of HNSCC in vitro and in vivo were examined through the downregulation or upregulation of LINC01123, B7–H3, and miR-214-3p." (PMID 35115487, 2022). "Consistent with the fact that c-Myc holds significant roles in driving metabolic adaptation, our findings suggest a model that LINC01123/c-Myc positive feedback loop facilitates tumor malignant progression and metabolic reprogramming." (PMID 31488218, 2019). "The role of LINC01123 as a ceRNA has been comprehensively studied across a variety of tumors, revealing diverse mechanisms through which it influences tumor biology." (PMID 40255398, 2025). "This pathway suggests a critical role for LINC01123 in fostering an angiogenic tumor environment." (PMID 40255398, 2025). "Therefore, regulating LINC01123 expression levels can consequently control the rate of CCA tumor growth and metastasis." (PMID 39840861, 2025). "LINC01123 has emerged as a pivotal regulator in various types of cancer, exerting significant influence on tumor cell malignancy through intricate molecular mechanisms.For example, in OSCC and HCC, LINC01123 acts as a ceRNA by sequestering miR-34a-5p, which in turn upregulates TUFT1 expression." (PMID 40255398, 2025). "Collectively, these results suggest that LINC01123 is a tumor driver of HCC." (PMID 32760198, 2020). "Similarly, the transwell assay revealed that inhibition of LINC01123 or B7–H3 or enhancement of miR-214-3p reduced tumor invasion and migration ability (P < 0.05), while the opposite was seen when LINC01123 was overexpressed or miR-214-3p was inhibited (P < 0.05)." (PMID 35115487, 2022). "In triple-negative breast cancer (TNBC), LINC01123 is transcriptionally amplified by FOXC1, which directly binds to the LINC01123 promoter and promotes malignant cellular processes in tumor cells." (PMID 40255398, 2025). "By acting as a miRNA sponge, LINC01123 promotes TNBC progression, implicating its role in modulating cellular processes crucial for tumor growth and metastasis." (PMID 40255398, 2025). "In subsequent assays, we found that downregulation of LINC01123 and B7–H3 or upregulation of miR-214-3p reduced HNSCC tumor progression." (PMID 35115487, 2022).
tumor (continued). "Furthermore, LINC01123 plays a critical role in crucial biological processes such as epithelial-mesenchymal transition (EMT), tumor cell growth, and invasion." (PMID 40255398, 2025).
cancer (4 papers, 2019 to 2025). A tumor composed of atypical neoplastic, often pleomorphic cells that invade other tissues. "LINC01123 exhibits a crucial role in promoting resistance to treatment across different types of cancer." (PMID 40255398, 2025). "This regulatory interaction enhances cancer cell proliferation and invasion, highlighting LINC01123 as a potential therapeutic target to inhibit oncogenic processes." (PMID 40255398, 2025). "LINC01123 plays a pivotal role in enhancing resistance to treatment in various cancers by regulating ceRNA networks and influencing key downstream effectors." (PMID 40255398, 2025). "This work systematically elucidates its primary functions and molecular mechanisms driving cancer initiation and progression, suggesting that LINC01123 might serve as a novel potential oncogenic driver and biomarker in various cancers." (PMID 40255398, 2025). "LINC01123 is regulated by multiple transcription factors and participates in gene regulation through protein interactions and competitive endogenous RNA (ceRNA) networks, thereby modulating cancer-promoting effects." (PMID 40255398, 2025). "In conclusion, LINC01123 was overexpressed in HCC and accelerated cancer cell proliferation and invasion by regulating the miR-34a-5p/TUFT1 axis." (PMID 32760198, 2020).
LINC01123 also shares sentences with these, for which no sentence is quoted: endometrial cancer (1 paper); pancreatic cancer (1); prostate carcinoma (1).